CEPT1 (choline/ethanolamine phosphotransferase 1)
Description:
Catalyzes both phosphatidylcholine and phosphatidylethanolamine biosynthesis from CDP-choline and CDP-ethanolamine, respectively. Involved in protein-dependent process of phospholipid transport to distribute phosphatidyl choline to the lumenal surface. Has a higher cholinephosphotransferase activity than ethanolaminephosphotransferase activity.
Tractability: Small molecule: a structure with a bound ligand is known. Antibody: UniProt predicts a signal peptide or a membrane-spanning region. PROTAC: its protein half-life has been measured; a small molecule that binds it is known.
Target class: Enzyme; Transferase
Gene: Protein-coding gene on chromosome 1 (111,139,479 to 111,185,507, forward strand). Ensembl gene ENSG00000134255.
Subcellular location: Endoplasmic reticulum membrane; Nucleus membrane
Pathways (Reactome):
Metabolism: Synthesis of PC; Synthesis of PE
Gene Ontology:
Molecular function: 1-alkenyl-2-acylglycerol choline phosphotransferase activity; diacylglycerol cholinephosphotransferase activity; ethanolaminephosphotransferase activity; protein binding; phosphotransferase activity, for other substituted phosphate groups
Biological process: phosphatidylcholine biosynthetic process; phosphatidylethanolamine biosynthetic process; lipid metabolic process; phospholipid biosynthetic process
Cellular component: endoplasmic reticulum membrane; Golgi apparatus; membrane; cytoplasm; endomembrane system; nuclear membrane
Genetic constraint (gnomAD): Loss-of-function variants: 7 observed, 36.65 expected, observed/expected ratio (o/e) 0.19, 90% interval 0.11 to 0.36. The upper end of that interval is the gene's LOEUF score, 0.36, which puts it in group 1 of 6, group 1 being the genes least tolerant of losing a copy. Missense variants: 251 observed, 445.71 expected, observed/expected ratio (o/e) 0.56, 90% interval 0.51 to 0.62. Synonymous variants: 149 observed, 157.06 expected, observed/expected ratio (o/e) 0.95, 90% interval 0.83 to 1.09.
Homologues: Orthologues: chimpanzee CEPT1 (100% identical), macaque CEPT1 (99% identical), rabbit CEPT1 (99% identical), rat Cept1 (99% identical), mouse Cept1 (99% identical), dog CEPT1 (98% identical), guinea pig CEPT1 (98% identical), pig CEPT1 (96% identical), tropical clawed frog cept1 (83% identical), zebrafish cept1b (78% identical), zebrafish cept1a (76% identical), Drosophila melanogaster bbc (50% identical), and 2 more. Paralogues in human: CHPT1 (60% identical), SELENOI (24% identical).
Diseases named in the same sentence as CEPT1 in open-access papers:
CEPT1 is named in the same sentence as 18 diseases in open-access papers, as found by Europe PMC text mining. Sharing a sentence is not in itself a finding about the gene and the disease. The quoted sentences say what the papers report.
diabetes (4 papers, 2018 to 2023). "For example, choline-ethanolamine phosphotransferase 1 (CEPT1), a key regulator of de novo phospholipogenesis, is highly expressed in Min-diseased carotid arterial segments particularly in individuals with diabetes." (PMID 35783870, 2022). "Future investigations targeting CEPT1 and its downstream phospholipid ligands may provide new opportunities for the treatment of human atheroprogression in the setting of diabetes." (PMID 29478028, 2018). "Thus, in the setting of diabetes, it is evident that CEPT1 generates important phospholipid ligands that can increase tissue phospholipid content and oxidative stress." (PMID 29478028, 2018). "To provide novel insights into the complex relationship between diabetes and tissue phospholipogenesis, we tested the hypothesis that diabetic subjects have altered CEPT1 plaque expression and phospholipid content in variably diseased (MIN vs. MAX) carotid artery plaque segments." (PMID 29478028, 2018).
Insulin resistance (2 papers, 2019 to 2021). Increased resistance towards insulin, that is, diminished effectiveness of insulin in reducing blood glucose levels. "In the same context, other physiological changes may explain insulin resistance in obese subjects, such as the increase of fatty acid synthase (FAS) and choline/ethanolamine phosphotransferase 1 (CEPT1) enzymes activity, and/or expression." (PMID 34948944, 2021).
Obesity (2 papers, 2017 to 2018). Accumulation of substantial excess body fat. "Mice with a skeletal muscle CEPT1 deficiency have increased insulin sensitivity and altered muscle tissue lipid compartmentalization with diet-induced obesity." (PMID 29478028, 2018). "Mice with diet-induced obesity show an increased expression of Choline/Ethanolamine Phosphotransferase 1 (CEPT1), the muscle specific knockout of CEPT1 led to improved insulin sensitivity and levels of CEPT1 expression were inversely correlated with insulin sensitivity in obese human subjects." (PMID 28606124, 2017).
endothelial dysfunction (1 paper, 2022). In vascular diseases, endothelial dysfunction is a systemic pathological state of the endothelium (the inner lining of blood vessels) and can be broadly defined as an imbalance between vasodilating and vasoconstricting substances produced by (or acting on) the endothelium. "We previously observed similar expression patterns in CEPT1 metabolism in Max-diseased lower extremity arterial segments, suggesting that arterial lipid metabolism is significantly impacted by disease progression and endothelial dysfunction in these segments." (PMID 35783870, 2022).
glioblastoma (1 paper, 2023). The most malignant astrocytic tumor (WHO grade IV). "The association between higher CEPT1 expression and better patient outcomes in glioblastoma can be explained by lipid metabolism." (PMID 37046844, 2023). "However, GEPIA found a trend of better prognosis (p = 0.062) with higher CEPT1 expression in glioblastoma tumors." (PMID 37046844, 2023). "The higher expression of CEPT1 in glioblastoma tumors indicates greater biosynthesis of PE and PC than in healthy brain tissue, which explains the higher levels of these glycerophospholipids in glioblastoma tumors compared to healthy brain tissue." (PMID 37046844, 2023). "Therefore, to better understand glioblastoma, it is necessary to investigate these enzymes, especially PEMT, whose expression is increased in the glioblastoma tumor, and CEPT1, an enzyme that may impact the prognosis for glioblastoma patients." (PMID 37046844, 2023).
Glucose intolerance (1 paper, 2019). Glucose intolerance (GI) can be defined as dysglycemia that comprises both prediabetes and diabetes. "acs-13 mutations enhance the ability of mdt-15(et14) or cept-1(et10) to suppress the glucose intolerance of the paqr-2 mutant." (PMID 31769755, 2019).
inflammatory bowel disease (1 paper, 2023). A spectrum of small and large bowel inflammatory diseases of unknown etiology. "Notably, three of these genes (CEPT1, PHLPP1, USP3) were reported to directly or indirectly link to inflammatory bowel disease through experimental or bioinformatics methods." (PMID 38201909, 2023).
mesothelioma (1 paper, 2025). A usually malignant and aggressive neoplasm of the mesothelium which is often associated with exposure to asbestos. "Subsequently, ChIP assays revealed increased recruitment of p65 to the NF-κB enhancers of CCTα, CHPT1, and CEPT1 in mesothelioma cell lines compared to normal mesothelial cells (HMC35)." (PMID 40016284, 2025). "Given the elevated mRNA expression of phospholipid biosynthesis genes (CCTα, CHPT1, and CEPT1) in mesothelioma cell lines, we investigated the putative regulatory role of NF-κB." (PMID 40016284, 2025).
ovarian carcinoma (1 paper, 2014). A malignant neoplasm originating from the surface ovarian epithelium. "Similarly, three other genes, namely, CYP4B1, CEPT1, and CHMP4A are differentially regulated in patients who suffer from recurrent ovarian cancer disease." (PMID 27382614, 2014). "Another recent study integrated TCGA data and validated three genes (CYP4B1, CEPT1, and CHMP4A) in HGS-OvCa from patients likely to be cured by initial cytoreductive surgery and adjuvant chemotherapy; the precise role of these genes in ovarian cancer pathophysiology remains to be elucidated." (PMID 27382614, 2014).
type 2 diabetes (1 paper, 2022). "We have reported that elevated levels of high-density lipoprotein (HDL)-resident adipose triglyceride lipase and increased activity of choline/ethanolamine phosphotransferase 1 (CEPT1) may contribute to the atheroprotective effect in GCK-MODY compared to that in type 2 diabetes milletus (T2DM)." (PMID 36387841, 2022).
cancer (3 papers, 2024 to 2025). A tumor composed of atypical neoplastic, often pleomorphic cells that invade other tissues. "Moreover, a correlation analysis revealed a significant positive correlation between HIF‐1α and CEPT1 expression in the cancer tissues of GC patients." (PMID 40954549, 2025). "Moreover, there was a significant positive correlation between HIF‐1α and CEPT1 expression in the cancer tissues of GC patients." (PMID 40954549, 2025). "Therefore, blockade of the HIF‐1α/CEPT1/PC signalling axis has emerged as a promising therapeutic strategy for preventing cancer cell metastasis in GC." (PMID 40954549, 2025).
tumor (3 papers, 2024 to 2025). "The expression of HIF‐1α and CEPT1 in GC tumour tissues was significantly greater than that in adjacent tissues." (PMID 40954549, 2025). "As expected, IKE treatment increased the staining of 4-HNE, a marker of lipid peroxidation; moreover, the staining of 4-HNE was further intensified in CEPT1 knockout tumor samples treated with IKE, compared to control tumors treated with IKE." (PMID 38430542, 2024). "We observed that CEPT1 deletion did not impact the growth of HT-1080 xenograft tumors but rendered the tumors more susceptible to IKE treatment; consequently, CEPT1 knockout tumors treated with IKE exhibited reduced tumor growth compared to control tumors subjected to IKE treatment." (PMID 38430542, 2024).
CEPT1 also shares sentences with these, for which no sentence is quoted: metabolic disease (2 papers); alcohol use disorders (1); infection (1); ischemic stroke (1); liver disorder (1); spondylometaphyseal dysplasia (1).